DKK4 (dickkopf Wnt signaling pathway inhibitor 4)
Description:
Antagonizes canonical Wnt signaling by inhibiting LRP5/6 interaction with Wnt and by forming a ternary complex with the transmembrane protein KREMEN that promotes internalization of LRP5/6. DKKs play an important role in vertebrate development, where they locally inhibit Wnt regulated processes such as antero-posterior axial patterning, limb development, somitogenesis and eye formation. In the adult, Dkks are implicated in bone formation and bone disease, cancer and Alzheimer disease (By similarity).
Synonyms: Dkk-4
Tractability: Antibody: UniProt places it where antibodies can reach, with medium confidence; UniProt predicts a signal peptide or a membrane-spanning region; its Gene Ontology location is reachable by antibodies, with medium confidence.
Gene: Protein-coding gene on chromosome 8 (42,374,063 to 42,377,229, reverse strand). Ensembl gene ENSG00000104371.
Subcellular location: Secreted
Pathways (Reactome):
Signal Transduction: Negative regulation of TCF-dependent signaling by WNT ligand antagonists; TCF dependent signaling in response to WNT
Disease: Signaling by LRP5 mutants
Gene Ontology:
Molecular function: protein binding; co-receptor binding; receptor antagonist activity
Biological process: negative regulation of canonical Wnt signaling pathway; negative regulation of Wnt signaling pathway
Cellular component: extracellular region
Genetic constraint (gnomAD): Loss-of-function variants: 20 observed, 17.65 expected, observed/expected ratio (o/e) 1.13, 90% interval 0.8 to 1.64. The upper end of that interval is the gene's LOEUF score, 1.64, which puts it in group 6 of 6, group 1 being the genes least tolerant of losing a copy. Missense variants: 272 observed, 293.99 expected, observed/expected ratio (o/e) 0.93, 90% interval 0.84 to 1.02. Synonymous variants: 89 observed, 111.53 expected, observed/expected ratio (o/e) 0.8, 90% interval 0.67 to 0.95.
Homologues: Orthologues: chimpanzee DKK4 (99% identical), macaque DKK4 (96% identical), pig DKK4 (83% identical), dog DKK4 (79% identical), rat Dkk4 (75% identical), mouse Dkk4 (75% identical), guinea pig DKK4 (65% identical).
Diseases named in the same sentence as DKK4 in open-access papers:
DKK4 is named in the same sentence as 49 diseases in open-access papers, as found by Europe PMC text mining. Sharing a sentence is not in itself a finding about the gene and the disease. The quoted sentences say what the papers report.
colorectal cancer (13 papers, 2006 to 2024). A primary or metastatic malignant neoplasm that affects the colon or rectum. "Our results are contradicting to the previous observations and indicate that DKK4 acts as a key factor of poor prognosis of patients with colorectal cancers and promotes the CRC metastasis in mouse models." (PMID 38519641, 2024). "The DKK4 expression level in colorectal cancer cells was significantly higher than that in FHC cells." (PMID 36181792, 2022). "In our study, we found that high DKK4 expression is correlated with prolonged survival in colorectal cancer patients." (PMID 36181792, 2022). "The results showed that DKK4 was overexpressed in the colonic mucosa of patients with colitis and in several colorectal cancer cell lines." (PMID 33586359, 2021). "On the contrary, activation of DKK4 expression was observed in colorectal cancer cell lines by the antitumor histone deacetylase inhibitor trichostatin A (TSA)." (PMID 33586359, 2021). "These enhanced effects were concomitant to TFAP2E upregulation and DKK4 downregulation, as shown with 5-FU resistance in colorectal cancer." (PMID 29383097, 2017). "Taken together, our results suggest that DKK4 acts as an oncogene in colorectal cancers." (PMID 38519641, 2024). "DKK4 is downregulated in hepatocellular carcinoma and is upregulated in many other cancers, including ovarian cancer, renal cell carcinoma, gastric cancer, and colorectal cancer (CRC)." (PMID 38519641, 2024). "DKK4 might be involved in the invasion of epithelial ovarian cancer, inhibits the invasion of hepatocellular carcinoma and colorectal carcinoma, and suppresses colorectal cancer metastasis." (PMID 38519641, 2024). "DKK4 has been demonstrated to be involved in fluorouracil resistance in colorectal cancer." (PMID 37291585, 2023). "Overexpression of DKK4 in colorectal cancer was also previously reported." (PMID 36293321, 2022). "To investigate the DKK4 expression pattern in CRC, we detected DKK4 mRNA levels by quantitative real-time PCR (qRT‒PCR) and protein levels by Western blot in 23 colorectal cancer cell lines and an immortalized human normal intestinal epithelial cell line (FHC)." (PMID 36181792, 2022). "Several lines of evidence suggested that DKK4 may be involved in chemotherapy resistance in colorectal cancer and it was revealed that DKK4 was overexpressed in multiple colorectal cancer cell lines." (PMID 33586359, 2021). "The earlier studies suggested that DKK4 was down-regulated in human tumors, for example in hepatocellular carcinoma and colorectal cancer, which indicated that DKK4 might act as a tumor suppressor by inhibiting Wnt/β-catenin signaling." (PMID 28666421, 2017). "This is the first report to show that DKK4 may play an important role in colorectal cancer possibly via the Wnt signaling pathway." (PMID 16584549, 2006). "Therefore, it was proposed that DKK4 could be a good target gene for TFAP2E hypermethylation positive colorectal cancer patients if they were TFAP2E‐mediated chemoresistance." (PMID 33586359, 2021). "TFAP2E, on the other hand, perturbs the Wnt/β-catenin signaling by transcriptionally inhibiting the expression of dickkopf Wnt signaling pathway inhibitor 4 (DKK4), an antagonist of Wnt signaling that occupies the Wnt coreceptor, in colorectal cancer." (PMID 37291585, 2023). "Although the mechanism is different, it is consistent with the previous study in colorectal cancer cells; TET1 also inhibits the Wnt pathway indirectly by promoting the expression of Wnt suppressors DKK3 and DKK4 to, therefore, prohibit cell proliferation." (PMID 35805009, 2022). "In the present study, we found that DKK4 is highly expressed among 23 colorectal cancer cell lines and 229 CRC tissues, and high DKK4 expression correlates with a longer survival time of CRC patients." (PMID 36181792, 2022). "DKK4 was overexpressed in MTCM918T (Medullary thyroid carcinoma) and colorectal cancer, and this upregulation reflects the activation of the canonical Wnt pathway." (PMID 33586359, 2021).
colorectal cancer (continued). "Experiment results showed that DKK4 alone or in combination enhanced the resistance to 5‐Fu and YN968D1 treatment in colorectal cancer cells." (PMID 33586359, 2021). "It was confirmed that DKK4 was the downstream target gene of TFAP2E hypermethylation and that TFAP2E‐dependent drug resistance was achieved by targeting DKK4 in colorectal cancers." (PMID 33586359, 2021). "DKK4 expression was upregulated in Renal Cell Carcinoma (RCC), Colorectal Cancer, Gastric Cancer (GC), Non‐small Cell Lung Cancer (NSCLC) and Epithelial Ovarian Cancer (EOC), while downregulated in Hepatocellular Carcinoma (HCC)." (PMID 33586359, 2021). "In colorectal cancer cells, TCF7l1 recruits both CtBP and HDAC1 to repress expression of the Wnt antagonist DICKKOPF4 (DKK4)." (PMID 34901027, 2021).
hepatocellular carcinoma (11 papers, 2013 to 2024). A malignant tumor that arises from hepatocytes. "However, DKK4 expression was shown to be associated with decrease in hepatoma cells progression induced by thyroid hormones and has been marked as tumor suppressor gene in hepatocellular carcinoma." (PMID 33346226, 2020). "Another study showed that a high-glucose medium activates the Wnt/β-catenin pathway in hepatocellular carcinoma by reducing the expression of DKK4, a Wnt pathway inhibitor." (PMID 39766346, 2024). "Our present findings are similar to other reports showing that the upregulation of DKK4 by T3 inhibited the invasion and metastasis of hepatoma cells through the degradation of β-catenin." (PMID 37096225, 2023). "High glucose induced activation of Wnt/β-catenin pathway in hepatocellular carcinoma cells by inhibiting dickkopf 4 (DKK4, a Wnt antagonist)." (PMID 34060533, 2021). "Recent findings demonstrated that DKK4 overexpression suppressed migration, invasion, and tumor formation of human hepatoma cells in mice." (PMID 28273073, 2017). "Tumor suppression role of DKK3 protein was found in human cancers in ovary, cervix and colon; and expression of DKK4 protein was reduced in hepatocellular carcinoma tissue and could decrease the β-catenin protein levels." (PMID 27457487, 2016). "In addition, the upregulation of DKK4 by T3 suppressed hepatoma cell metastasis." (PMID 33586359, 2021).
breast cancer (9 papers, 2007 to 2025). A primary or metastatic malignant neoplasm involving the breast. "Interestingly, homozygosity of the minor allele (T) in the DKK4 gene (rs3763511) posed significantly increased risk of ER- breast cancer (OR, 16.7; CI, 0.838–334.06; p = 0.00932)." (PMID 23516639, 2013). "Surprisingly, we found that 1,25(OH)2D3 inhibits DKK-4 expression in human colon and breast cancer cells and that DKK-4 overexpression in human colon cancer cells increases their migratory, invasive and angiogenic capacities." (PMID 24202444, 2013). "Furthermore, downstream Wnt/β-catenin target genes, including CCND1, Jun, Axin2, and Dickkopf 4 (Dkk4), are upregulated in mammary tumors in BK5.ATF3 mice." (PMID 32922364, 2020). "SNP rs3763511 in DKK4 was related with age independent increased breast cancer risk of estrogen receptor negative tumor." (PMID 27457487, 2016). "Conversely, SNP in DKK-4 gene was strongly associated with age independent increased breast cancer risk of estrogen receptor negative tumor." (PMID 25945348, 2015). "As for DKK4, our findings indicate its significant down-regulation in breast cancer, however, the DKK4 gene is devoid of a CpG island, the typical target of epigenetic regulation, thus further investigations of the molecular mechanism for DKK4 down-regulation and its biological functions are needed." (PMID 23890219, 2013). "We did not observe statistically significant association with the risk of developing breast cancer for the SNPs in APC, DKK4 and LRP6 as well as some of the SNPs in β-catenin (rs13072632), AXIN2 (rs4791171, rs11079571 and rs3923086) and SFRP3 (rs288326) in the overall study population." (PMID 23516639, 2013). "Additionally, the rs3763511 in DKK4 that did not display any association in the overall as well as age related analysis was strongly associated with increased risk of ER- breast cancer." (PMID 23516639, 2013). "Other inhibitors of the Wnt signalling pathways including Dkk-4, which has been recently shown to be expressed in primary breast tumours could also play a role in the pathogenesis of breast cancer bone metastases." (PMID 17876334, 2007). "In MMTV.neu mammary tumors in which the Wnt/β-catenin pathway is not involved, expression of Axin2 was extremely low (relative expression 0.01 compared to BK5.ATF3 mammary glands, p<0.01, data not shown), and Dkk4 was undetectable." (PMID 21304988, 2011).
colon carcinoma (9 papers, 2010 to 2023). "In colon tumor cells, modulation of the angiogenic phenotype is also mediated by the control of genes encoding inhibitors of differentiation (ID)-1/2 and by the repression of DKK4, a weak Wnt antagonist that promotes angiogenesis and invasion and is upregulated in colon tumors." (PMID 35406059, 2022). "We first mined the TCGA-COAD data setto investigate the effect of high DKK3 and DKK4 expression on survivalprobability in a cohort of colon cancer patients." (PMID 36450103, 2023). "In summary, 1,25(OH)2D3 played a complex regulatory role in colon cancer cells, and this was mediated in part by DKK4." (PMID 33586359, 2021). "Some of these inhibitors are Wnt target genes, for example, DKK4, an inhibitor that is expressed in human colon cancer, and SFRP2, a secreted Wnt inhibitor induced by Wnt4 in the developing kidney." (PMID 28183841, 2017). "We and others found that DKK-4 is overexpressed in human colon tumors and in colon samples from patients with inflammatory bowel disease." (PMID 24202444, 2013). "In colon cancer cells, Dkk4 was shown to promote cell migration in a Wnt-independent cascade, so that an action on hair follicle development through a Wnt-independent pathway cannot be completely excluded at present." (PMID 20386733, 2010). "Dkk4 expression was also reported in human esophageal epithelium, and was up-regulated in endometrial and colon cancer tissues." (PMID 20386733, 2010). "Reduced expression of TET1 is expected to result in direct deregulation of parathyroid target genes, as for example described in colon cancer for the DKK3 and DKK4 inhibitors of the WNT pathway." (PMID 26973719, 2016).
ovarian carcinoma (6 papers, 2017 to 2024). A malignant neoplasm originating from the surface ovarian epithelium. "Two proteins were associated with the risk of ovarian cancer, DKK4 and WFDC2 [1.46 (1.28–1.70), 1.57 (1.26–1.96)]." (PMID 38750076, 2024). "Studies have demonstrated the tumor-promoting role of DKK4 in renal cell carcinoma, non-small cell lung cancer, and ovarian cancer." (PMID 36181792, 2022). "We detected the effect of DKK4 siRNA on ovarian cancer cell invasion (control siRNA vs. DKK4 siRNA) and the invasion ability of normal SKOV-3 and HO-8910 cells." (PMID 28666421, 2017). "Till now, the expression and role of DKK4 in cancer invasion especially in epithelial ovarian cancer remained unclear." (PMID 28666421, 2017). "The result of immunohistochemistry analysis showed that DKK4 was positively expressed in epithelial ovarian cancer samples." (PMID 28666421, 2017). "The reason why DKK4 overexpression predicted poor prognosis for ovarian cancer patients and promoted invaion was unclear." (PMID 28666421, 2017). "This study detected the clinical significance of DKK4 in epithelial ovarian cancer (EOC) patients and its role in invasion." (PMID 28666421, 2017). "Meanwhile the strong expression of DKK4 protein in ovarian cancer samples was positively correlated with late FIGO stage with p = 0.005." (PMID 28666421, 2017). "Additionally, hsa_circ_0000735 was found to be involved in docetaxel-resistance in ovarian cancer via the hsa_circ_0000735/miR-546b/Dickkopf-related protein 4 (DKK4)/P-glycoprotein (p-GP) axis." (PMID 35205613, 2022). "However, DKK4 is overexpressed in pancreatic cancer, ovarian cancer, gastric cancer, and non-small cell lung cancer." (PMID 36181792, 2022). "In this study, our data supported a new role for DKK4 in human epithelial ovarian cancer." (PMID 28666421, 2017). "Our results showed that DKK4 knockdown significantly decreased the incidence of invasion in ovarian cancer cells (SKOV-3: control siRNA (177.97 ± 29.59) vs. DKK4 siRNA (49.43 ± 23.57), p < 0.0001; HO-8910: control siRNA (167.63 ± 11.91) vs. DKK4 siRNA (53.23 ± 4.41), p < 0.0001)." (PMID 28666421, 2017). "The effect of DKK4 on the ovarian cancer cells remains unclear." (PMID 28666421, 2017). "In patients with epithelial ovarian cancer (EOC), immunohistochemical results showed that strong expression of DKK4 protein was positively correlated with advanced FIGO stage (P =.005) and poor disease‐free survival in univariate and multivariate analysis (P <.0001 and P =.001, respectively)." (PMID 33586359, 2021). "DKK4 was strong expressed in 148/239 ovarian cancer samples, weak expressed in 72/239 ovarian cancer samples, while negative expressed in only 19/239 ovarian cancer samples." (PMID 28666421, 2017).
liver cancer (4 papers, 2016 to 2022). An epithelial or non-epithelial malignant neoplasm that arises from the liver. "In contrast, DKK4 is commonly considered a tumor suppressor in gastrointestinal cancers such as liver cancer and gastric cancer." (PMID 36181792, 2022). "DKK4 is positively regulated by T3 and TR in liver cancer, and PGCP liberates T4 from the N-terminus of Tg." (PMID 27806330, 2016). "Here we report a novel mechanism by which secreted plasma glutamate carboxypeptidase(PGCP) negatively involves Wnt/β-catenin signaling by DKK4 regulation in liver cancer metastasis." (PMID 27806330, 2016). "It was reported that DKK4 expression is silent in liver cancers." (PMID 33586359, 2021). "Given this information, we hypothesized that PGCP may be a negative regulator of liver cancer metastasis by inducing DKK4 expression and thereby blocking Wnt/β-catenin signaling." (PMID 27806330, 2016). "Notably, T3 induced the expression of DKK4, a well-known antagonist of Wnt/β-catenin signaling pathway, and suppressed cell invasion in liver cancer cells suggesting a role of T3 as a tumor suppressor." (PMID 27806330, 2016). "In conclusion, we report for the first time that PGCP blocks liver cancer metastasis through the inactivation of Wnt/β-catenin signaling by regulating DKK4 expression and thus may represent an effective target for control of liver metastasis." (PMID 27806330, 2016). "However, the addition of DKK4 protein could repress the Wnt/β‐catenin activation and liver cancer metastasis." (PMID 33586359, 2021). "DKK4 suppresses cell invasion, whereas DKK1 promotes invasion and metastasis in serous ovarian cancer and liver cancer." (PMID 27806330, 2016). "Thus, there are likely additional mechanisms independent of SRC-2 that control DKK4 expression in liver cancer cells." (PMID 28273073, 2017). "Our data also suggest that DKK4 and THRSP may not be targets of SRC-2 in HepG2 cells, and thus may be dysregulated in liver cancer cells through additional SRC-2-independent mechanisms." (PMID 28273073, 2017).
pancreatic cancer (4 papers, 2017 to 2025). "Nevertheless, the overexpression of both DKK1 and DKK4 has been observed in pancreatic cancers and proposed as potential therapeutic targets." (PMID 39245631, 2025). "They established a pancreatic cancer cell line with DKK4 overexpression and identified the differentially expressed genes (DEGs) by transcriptional sequencing." (PMID 33586359, 2021).
renal carcinoma (4 papers, 2012 to 2021). A carcinoma arising from the epithelium of the renal parenchyma or the renal pelvis. "Although DKK4 overexpression was found in some cancers, like, colon, pancreatic, and renal cancer, limited information was available on the role of DKK4 protein in predicting cancer prognosis." (PMID 28666421, 2017). "They suggested 10 proteins for renal cancer exsome biomarker, 5 of which are abundant in renal cancer patients; matrix metalloproteinase 9 (MMP-9), ceruloplasmin (CP), podocalyxin (PODXL), dickkopf related protein 4 (DKK4) and carbonic anhydrase IX (CAIX)." (PMID 31686989, 2019). "It's found that the high expression of DKK4 in renal cancer tissues activated the noncanonical JNK signalling pathway while inhibited the canonical Wnt pathway." (PMID 33586359, 2021). "DKK4 could also promote cell proliferation, invasion, and migration by activating the noncanonical c-Jun-NH2 kinase signaling pathway in renal cancer." (PMID 28666421, 2017).
gastric cancer (3 papers, 2014 to 2022). A primary or metastatic malignant neoplasm involving the stomach. "DKK-4 was found to show high specificity for gastric cancer." (PMID 25116444, 2014).
lung cancer (3 papers, 2020 to 2022). A malignant neoplasm involving the lung. "Another recent study confirmed that DKK4: rs2073664 along with three polymorphisms (rs447372, rs419558, and rs17037102) of DKK2 within the Wnt signaling pathway could jointly predict the survival of lung cancer patients who were treated with platinum-based doublet chemotherapy." (PMID 32453708, 2020).